NIHCOLE (ncRNA involved in NHEJ oncogenic ligation efficiency)
Synonyms: RP11-138J23.1; formerly LINC02163
Gene: Long non-coding RNA gene on chromosome 5 (104,063,083 to 104,430,245, forward strand). Ensembl gene ENSG00000251026.
Diseases named in the same sentence as NIHCOLE in open-access papers:
NIHCOLE is named in the same sentence as 2 diseases in open-access papers, as found by Europe PMC text mining. Sharing a sentence is not in itself a finding about the gene and the disease.
NIHCOLE shares sentences with these, for which no sentence is quoted: gastric cancer (1 paper); tumor (1).